APTX (aprataxin)
Diseases named in the same sentence as APTX in open-access papers (continued):
Sharing a sentence is not in itself a finding about the gene and the disease.
colorectal cancer (2 papers, 2013 to 2019). A primary or metastatic malignant neoplasm that affects the colon or rectum. "Validation in a panel of 30 colorectal cancer cell lines, the levels of APTX were significantly associated with CPT sensitivity (P = 0.004)." (PMID 23517622, 2013). "A previous report showed that targeted inactivation of APTX significantly sensitized cells to camptothecin (an anti-cancer drug) treatment in colorectal cancer cell lines." (PMID 31448237, 2019). "A previous study into the expression of APTX demonstrated that increased APTX expression could regulate the cellular sensitivity to anticancer drug resistance in patients with advanced colorectal cancer." (PMID 31448237, 2019).
gastric cancer (2 papers, 2013). A primary or metastatic malignant neoplasm involving the stomach. "Future studies including more genes (such as TOP-I, PARP, and Aprataxin(APTX)) will be carried out to identify and target the most sensitive gastric cancer subpopulation for personalized CPT-11 therapy." (PMID 24359226, 2013). "We examined gene expression of APTX, BRCA1, ERCC1, ISG15, Topo1 and methylation of SULF2 in formalin-fixed paraffin-embedded gastric cancer tissues from 175 patients and evaluated the association between gene expression levels or methylation status and in vitro sensitivity to irinotecan." (PMID 23517622, 2013). "As a supplement to the previous studies, the current study further demonstrated that higher APTX, BRCA1 and ERCC1 mRNA expression levels suggested lower likelihood of response to irinotecan-based chemotherapy in gastric cancer." (PMID 23517622, 2013). "Gene expression levels of APTX, BRCA1 and ERCC1 were significantly lower in irinotecan-sensitive gastric cancer samples than those irinotecan-resistant samples (P < 0.001 for all genes), while ISG15 (P = 0.047) and Topo1 (P = 0.002) were significantly higher." (PMID 23517622, 2013).
hereditary ataxia (2 papers, 2017 to 2024). An instance of an atactic disorder that is caused by an inherited genomic modification in an individual. "Of these, two genes, including APTX, were previously reported to be associated with hereditary ataxia (Bird 1993; Jayadev and Bird 2013)." (PMID 28652255, 2017). "Using whole-exome sequencing (WES), we are able to identify a novel mutation in the APTX gene in a consanguineous Iranian family with hereditary ataxia." (PMID 28652255, 2017).
Intellectual disability (2 papers, 2025). "TGex analysis (LifeMap Sciences, USA) prioritized 9 candidate variants across 7 genes (MED13, POGZ, SETBP1, SCN9A, SCO1, APTX, TIE1) associated with phenotypes including congenital megacolon, intellectual disability, motor delay, and developmental delays." (PMID 41195223, 2025).
osteosarcoma (2 papers, 2023). A usually aggressive malignant bone-forming mesenchymal neoplasm, predominantly affecting adolescents and young adults. "Here, we generated APTX knock-out (APTX−/−) cell from human osteosarcoma U2OS through CRISPR/Cas9-mediated genome editing system." (PMID 36940705, 2023).
acute myelogenous leukemia (1 paper, 2012). "A recent clinical trial in patients with acute myelogenous leukemia has shown that patients whose tumor cells have a high ratio of expression of two genes, RASGRP1 and APTX, are more likely to respond to R115777." (PMID 23228035, 2012).
congenital heart disease (1 paper, 2024). A heart disease that is present at birth. "Our result was in agreement with the previous studies regarding most of the clinical manifestations; however, our patient had congenital heart disease and poor retinal function that were not previously reported in APTX gene mutations thus expanding its phenotypic spectrum." (PMID 38153683, 2024).
gastric tumors (1 paper, 2013). "To explore whether Pt, 5-FU and CPT-11 associated gene is involved in the anticancer effects of PPI and EVO on the freshly-removed gastric tumors, we first examined the mRNA expression levels of ERCC1, TS, TOPO1 and APTX in the samples before any drugs administration." (PMID 23762305, 2013).
Immunodeficiency (1 paper, 2023). Failure of the immune system to protect the body adequately from infection, due to the absence or insufficiency of some component process or substance. "APTX impairment has been linked to immunodeficiency and mitochondrial dysfunction." (PMID 38161589, 2023).
measles (1 paper, 2023). A highly contagious viral infection caused by the measles virus. "In NS cells, analysis found that many pathways enriched in WT compared to APTX KO were related to viral infections (such as measles, Epstein–Barr virus infection, and influenza A), but also to immune related pathways (NOD-like receptor signaling) and inflammatory pathways (NF-kB signaling pathway)." (PMID 38161589, 2023).
melanoma (1 paper, 2021). A malignant, usually aggressive tumor composed of atypical, neoplastic melanocytes. "In melanoma brain metastases, heterozygous copy number loss of HR and SSB repair, but no mismatch repair-associated genes, was found, which from the most prevalent genes were APTX, FEN1, GTF2H5, DNA2, MUS81 and TOP3A." (PMID 34885093, 2021).
viral infections (1 paper, 2023). "Enrichment analysis identified a dysregulated response to viral infections and a dysregulated innate immune response in APTX deficient cells." (PMID 38161589, 2023). "RNA-seq analysis revealed significant differences in the transcriptomes of wild-type and APTX knockout cells, especially in response to viral infections and innate immune pathways." (PMID 38161589, 2023). "Along with differences in response to viral infection, this analysis provides evidence that KO of APTX results in altered innate immunity as NOD-like receptor signaling has been described as a master regulator of innate immunity." (PMID 38161589, 2023). "A large number of pathways relating to viral infection, as well as inflammatory and immune pathways, were enriched in WT cells but not in APTX KO cells." (PMID 38161589, 2023).
cancer (9 papers, 2015 to 2024). A tumor composed of atypical neoplastic, often pleomorphic cells that invade other tissues. "In this current study, through genome-wide RNA-Seq profile analysis of post-Tx malignant blood samples and post-Tx non-malignant control blood samples (CTRL-Tx), we found Rap GTPase Interactor (RADIL) and Aprataxin (APTX) to be the most meaningful markers for cancer diagnosis." (PMID 31448237, 2019). "APTX stimulates DNA repair and protects cells against genotoxic stress in cancer cell." (PMID 27769049, 2016). "A number of aging- and cancer-associated genes were observed among the 420 predicted bowhead-minke orthologs with dN/dS exceeding 1, including suppressor of cytokine signaling 2 (SOCS2), aprataxin (APTX), noggin (NOG), and leptin (LEP)." (PMID 25565328, 2015). "Downregulation of APLF (Aprataxin and PNK-like factor) inhibited cancer cell proliferation, altered cell cycle behavior, induced apoptosis, and impaired DNA repair ability." (PMID 39202384, 2024). "Thus, rational design of inhibitors that modulate APTX‐DNA‐end and DNA‐nick deadenylation activities stemming from this work could be useful for treatment of cancers, or as a co‐therapy with existing chemotherapeutics that induce “dirty” complex structured DNA breaks." (PMID 29934293, 2018). "The presence or absence of APTX did not impact cancer prevalence, and mice with at least one Atm transcript were cancer-free up until at least P400." (PMID 34723800, 2021). "Further research is needed; however, cancer patients with both high RPL11 and low APTX expression may display higher treatment sensitivity to topoisomerase inhibitors than those with either high RPL11 or low APTX expression alone." (PMID 36555627, 2022).
neurodegenerative disease (9 papers, 2008 to 2024). A disorder of the central nervous system characterized by gradual and progressive loss of neural tissue and neurologic function. "Mutations or loss of function in DNA repair proteins like aprataxin (APTX), tyrosyl-DNA phosphodiesterase 1 (TDP1), or ataxia telangiectasia mutated kinase (ATM) have well-known associations with neurodegenerative diseases." (PMID 39000135, 2024). "Given the clinical consequences of LOF mutations in APTX, it is noteworthy that genetic variants in the HNRNP family of genes have been linked to neurodegenerative diseases." (PMID 38161589, 2023). "Furthermore, results from a comprehensive structural and functional characterization of AOA1 mutants provide a framework for understanding APTX inactivation in neurodegenerative disease." (PMID 29934293, 2018). "Our integrated APTX functional and structural studies provide testable structural paradigms for DNA‐nick and DNA‐end cleansing enzymes in the DNA damage response pathways, and better establish a molecular platform for understanding APTX dysfunction in neurodegenerative disease." (PMID 29934293, 2018).
neurological diseases (6 papers, 2015 to 2025). "Third, this work defines a detailed framework for understanding and categorizing the impacts of APTX catalytic domain missense and nonsense substitutions linked to AOA1 neurological disease." (PMID 29934293, 2018). "Recently it has been clearly documented that deficiencies in DNA end-processing activity (such as that of PNKP, TDP1 and Aprataxin) are linked to neurological diseases." (PMID 25633985, 2015). "Furthermore it has previously been shown that neurological disorders caused by mutations in the gene APTX coding for aprataxin are probably caused by accumulation of unrepaired DNA strand breaks resulting from abortive DNA ligation, generated especially by oxidation." (PMID 25867024, 2015).
tumor (6 papers, 2012 to 2019). "Lastly, this tumor has a SNV in the gene APTX that encodes for a protein involved in DNA repair that could convey sensitivity to irinotecan." (PMID 24204627, 2013). "Irinotecan treatment results in the accumulation of DNA strand breaks in tumor cells, and APTX, BRCA1 and ERCC1 have been shown to have important roles in the repair of DNA single- and double-strand breaks." (PMID 23517622, 2013). "However, a strong correlation was observed between the mRNA expression levels of APTX and BRCA1 (rho = 0.53, P < 0.001), APTX and ERCC1 (rho = 0.73, P < 0.001), BRCA1 and ERCC1 (rho = 0.48, P < 0.001) in tumor." (PMID 23517622, 2013).
movement disorder (2 papers, 2020). Neurological conditions resulting in abnormal voluntary or involuntary movement, which may impact the speed, fluency, quality and ease of movement. "It expands the spectrum of pathogenic APTX mutations associated with AOA1 and emphasizes the need of for genetic testing in patients with inherited movement disorders in patients from the Middle East, to assess the spread of founder mutations among consanguineous families." (PMID 32750061, 2020).
APTX also shares sentences with these, for which no sentence is quoted: cerebellar ataxia (7 papers); Dystonia (4); autosomal recessive cerebellar ataxia (3); cardiofaciocutaneous syndrome (3); cerebellar degeneration (3); Chorea (3); Friedreich ataxia (3); Nijmegen breakage syndrome (3); progressive ataxia (3); spinocerebellar ataxia with axonal neuropathy- (3); axonal neuropathy (2); Choreoathetosis (2); LIG4 syndrome (2); metastatic colorectal cancer (2); mitochondrial disease (2); myopathy (2); neuropathy (2); xeroderma pigmentosum (2); abetalipoproteinemia (1); asthma (1); Ataxia with vitamin E deficiency (1); ataxia-telangiectasia-like disorder (1); atrophies (1); Autosomal-recessive spinocerebellar ataxia 1 (1); chronic fatigue syndrome (1); cognitive decline (1); Cognitive impairment (1); congenital megacolon (1); developmental delays (1); DNA repair deficiency disorders (1).
A further 23 diseases each share a sentence with APTX in 1 paper.